CD4 (CD4 molecule)
Diseases named in the same sentence as CD4 in open-access papers (continued):
Sharing a sentence is not in itself a finding about the gene and the disease.
depression (continued). "In Uganda, among a sample of 1017 HIV infected persons, 47% scored in the elevated range on the Center for epidemiological studies-depression scale, with those with low CD4 counts more than twice as likely to report elevated depressive symptoms than those with high CD4 counts." (PMID 29651302, 2018). "Moreover, in several studies, depression has been found to be associated with higher HIV viral loads and lower CD4 counts, even after controlling for the effects of adherence, which predict a worsening disease progression and mortality." (PMID 29855289, 2018). "Higher prevalence of depression was associated with current or previously received ART treatment or having a CD4 count < 350 cells/mm3 compared to never using ARTs and having a CD4 count > 350 cells/mm3." (PMID 29590151, 2018). "Having more than 2-year duration on ART follow-up, experiencing, adverse ART drug effect, substance use, living with parents, having depression symptom, CD4 cell count <350 cells/mm3 and low dietary diversity were all found independent determinant factors of non-adherence of ART drug." (PMID 28331527, 2017). "We also showed that the presence of depression symptoms was associated with lower CD4 cell counts and an overall increase in the length of non-adherence." (PMID 28141867, 2017). "For example, recently released prisoners of war, women who suffer from PTSD from prior child abuse, children who suffer abuse, women with depression, and individuals exposed to standardized laboratory stressors have higher levels of CD4+ T-cell activation compared to unstressed controls." (PMID 27668294, 2016). "In addition, bivariate analysis was carried with the health status characteristics of the respondents such as type of care (ART/pre-ART), HIV clinical staging and CD4 count and depression." (PMID 27548753, 2016). "Additionally, the relationship between the manifestation of depression and its impact on clinical markers such as CD4+ cell counts and HIV plasma viral loads remains elusive." (PMID 27478681, 2016). "Although this is the first study to examine the effect of hip fracture and depression on IL10 production by CD4+ T cells, a few studies examining the effect of chronic stress such as caregiving and academic stress have reported increased IL10 production and secretion." (PMID 26112234, 2016). "This makes the diagnosis of PML particularly challenging, as transient states of immunodepression or immunodysfunction may not always be apparent, and the number of additional conditions ranges from idiopathic CD4+ depression to solid tumor malignancies." (PMID 27529042, 2016). "Here we have now shown the effects of chronic stress (hip fracture and depression) on two regulatory immune cell subsets; CD4+CD25+Foxp3+ (Tregs) and CD19+CD24hiCD38hi (Bregs) and again find that depressive symptoms are the factor determining the immune alterations." (PMID 26112234, 2016). "In addition, comorbid depression influences the decline rates of CD4+ cell counts and increases plasma viral load." (PMID 27478681, 2016). "Regression analysis showed that social support and depression variables could predict totally 47% (P<0.001) of changes of medication adherence variable, and depression could predict only 2% (P<0.01) of rate variance of CD4." (PMID 27157183, 2016). "At the standard position, the two groups have different levels of depression and CD4 counts." (PMID 25560348, 2014). "The retrospective study design limited our ability to gather data about factors that may influence morbidity, CD4 count and weight levels, such as food insecurity, social support and depression." (PMID 23573191, 2013). "However, very little is known about the immunological role that CD4+CD25+ Treg cells play in stress models of depression." (PMID 22860054, 2012). "Additionally, depression may play a more vital role in determining the immunologic response (CD4 + cell count) than behaviors such as ART adherence." (PMID 40133939, 2025).
depression (continued). "Research demonstrates that anxiety and depression in cancer patients can result in decreased appetite, nutritional deficiencies, and impaired sleep quality, creating a cycle that intensifies these psychological conditions and diminishes immune function, including CD8, CD4, and NK cells." (PMID 41446305, 2025). "However, patients with most CD4 counts of less than 200 cells/mm3 and those who took ART for ≤ 24 months and had chronic non-communicable diseases were at increased risk of developing depression." (PMID 38238489, 2024). "Additionally, depression may play a more vital role in determining the immunologic response (CD4 + cell count) than behaviors, e.g., ART adherence." (PMID 38168236, 2023). "Therefore, we hypothesized that inflammatory CD4+ Th17 cells may be involved in accelerating the development of depression and exacerbating disease symptoms." (PMID 35836182, 2022). "However, the clinical impact of CD4+ T cells and their corresponding cytokines on anxiety, depression, and cognitive impairment in elderly gastric cancer patients is unknown." (PMID 36386524, 2022). "Fourth, while data were not available in the current study on some other potential factors (e.g., physical exercise, depression, and some other medications) that might influence hair cortisol levels, CD4 count, and HIV viral load, those factors should be considered in future research." (PMID 35307019, 2022). "Thus, future studies designed to establish the pattern of association between the disturbance of Th CD4+ T lymphocytes and the clinical evolution of depression should include patients without pharmacological treatment." (PMID 33808804, 2021). "Similarly, symptomatic patients and those with CD4 count ≤ 200, the odds of depression was 2.51 [AOR = 2.51, 95% CI (1.38, 4.56)] and 5.94 [AOR = 5.94, 95% CI (2.68, 13.62)] times higher compared to those who were clinically stable and had higher CD4 count, respectively." (PMID 32742304, 2020). "Besides, HIV positive patients with comorbid diseases, such as depression or anxiety, are more likely to acquire viral resistance, and as a consequence, develop poor health outcomes due to low treatment adherence, especially decreased CD4 level." (PMID 32742296, 2020). "After logistic regression analysis; gender, high ACE and CD4 level were independently associated with current major depression, while only poor social support and contracting HIV infection after birth, were independently associated with lifetime major depression." (PMID 32818041, 2020). "Thus, it is likely that chronic or worsening NA may lead to a deterioration of immunological status, as defined by CD4 count, through a mediation of lowering treatment adherence, which was noted with respect to major depression in this patient group." (PMID 30097904, 2019). "Moreover, of two mediating variables (age & disease duration), only age could predict 3% (P<0.004) and of two predictive variables (depression & PTSD) only PTSD could predict 4% (P<0.001) of CD4 variance." (PMID 30847322, 2019). "Basic characteristics were entirely different such as CD4 cell count (209 cells/μL, range, 3–427 cells/μL versus 294 cells/μL, range, 29–465 cells/μL, p < 0.01) and psychiatric comorbidities (personality disorder, depression, psychotic disorder, and bipolar disorder, p < 0.01)." (PMID 30947701, 2019). "In addition, depression may also double the rate of CD4+ decline and negatively affects CD4+ counts at baseline." (PMID 27478681, 2016). "Therefore, controlling CD4+CD25+ Treg cell function during stress may be a potent therapeutic strategy for the treatment of depression-like symptoms." (PMID 22860054, 2012). "The comparison of gene expression profiling of CD4+ T cells in asthmatic subjects with and without depressive disorders can lead to the identification of genes implicated in such diseases and provide added insight into the underlying pathophysiological mechanisms." (PMID 23110234, 2012).
depression (continued). "Additionally, depression among patients with HIV is often associated with poor adherence to ART medication, which may lead to unsatisfactory viral load suppression and inadequate CD4 cell recovery." (PMID 40485941, 2025). "An early meta-analysis shows a link between depression, commonly observed in CFS/ME patients, and an increased CD4+/CD8+ ratio." (PMID 41463013, 2025). "Among PWH, NCI, depression, and HIV-disease characteristics (e.g., nadir CD4) have been related to everyday functioning impairment." (PMID 39928071, 2025). "Furthermore, abnormalities in peripheral CD4+ T cells have a key mediating role in mood disorders, and severe mitochondrial fission in CD4+ T cells can trigger purine metabolism disorders, which further lead to various behavioral abnormalities including anxiety, depression, and social disorders." (PMID 40405880, 2025). "Immune suppression in the absence of an immune response or via CD4+ regulatory T cell depletion has been linked with increased anxiety-like behavior, depression and alterations in social behavior and might in fact be one reason why marble burying is increased in our control NP + Orencia offspring." (PMID 38532505, 2024). "A study was also published, in which the search for factors common to depressive disorders and lichen planus highlighted two genes (NCAM1 and CD4) identified as common to the pathomechanism of both disorders." (PMID 38892934, 2024). "Studies have found the increased levels of CD4+ T cells in peripheral blood of MDD patients or groups with anxiety and depression symptoms." (PMID 37077528, 2023). "CD3+CD8+, CD4+ and CD3+CD25+ T-cell subsets were significantly unbalanced in patients with major depression, especially in women." (PMID 37238593, 2023). "Being female, low CD4 cell counts, viral load ≥1000 copies/ml, WHO stage II and III, depression, anxiety, sleeping in a communal bedroom, and living alone were predictors of poor sleep quality." (PMID 36864404, 2023). "Significant differences were observed between race/ethnicity, age group, BMI, insurance, unmet need, depression, smoking status, any drug use in the past 12 months, DM, HTN, HIV diagnosis duration, mean CD4 count, and durable viral load." (PMID 36123679, 2022). "We also found a significant correlation between mDI scores and the ratio of CD4 and CD8, suggesting an immune mechanism for depression." (PMID 35283726, 2022). "Decker, Kapila recently reported that chronic stress in the case of depression and post-traumatic stress disorder (PTSD) often presents with suppression of both the cellular and innate immune responses as CD4- and CD8-positive T helper cells." (PMID 36014842, 2022). "The outcomes are cancer fatigue scale, self-rating anxiety scales, self-rating depression scales, Pittsburgh sleep quality index, and immunity index (CD3+, CD4+, and CD8+) before and after the treatment." (PMID 34889240, 2021). "Secondary outcomes are HIV viral load and CD4 cell count at the 12-month assessment as well as ART adherence (Wisepill) and depression (HAM-D) over follow-up (4-, 8-, and 12-month assessments)." (PMID 32012114, 2020). "Offered the patient information about the relationship between depression and poor HIV outcomes (i.e. viral load impact, CD4 count, etc.)." (PMID 32292361, 2020). "We aimed to investigate the relationship between antiretroviral medication adherence and CD4 with posttraumatic stress disorder (PTSD) and depression in patients with HIV." (PMID 30847322, 2019). "Elevated CD8+ T lymphocytes and decreased CD4+ T lymphocytes have been previously reported in human immunodeficiency virus (HIV) and liver cirrhosis patients with co-morbid depression." (PMID 30885223, 2019). "For example, less than 1/3 of the studies reported the average or median counts of CD4 cells among HIV infected populations, and fewer than 10 studies provided employment-specific prevalence estimates of depression." (PMID 29855289, 2018).
depression (continued). "At baseline, HIV-positive women were more likely than HIV-negative women to have depression symptoms (81% vs. 65%, p < 0.0001) and HIV-positive women with CD4 counts below 200 were the most likely to have depression symptoms (OR = 4.97, CI 2.93, 8.45)." (PMID 29881448, 2018). "In terms of HIV disease progression, having depression can significantly increase plasma viral load—even after effective ART is initiated —and accelerate the decline of CD4+ cell counts." (PMID 27478681, 2016). "Additionally, severity of depression symptoms could explain almost 3% of CD4 rate variance." (PMID 27157183, 2016). "Depression has been shown to worsen HIV-related outcomes, including steeper declines in CD4 counts and more rapid progression to AIDS and death." (PMID 26503291, 2015). "This study investigated telomere length in cells of the adaptive immune system, namely CD4+ helper T cells, CD8+ cytotoxic T cells and CD20+ B cells in individuals with a history of unipolar depression vs. controls." (PMID 24996455, 2014). "Effect sizes (η2/η2p) indicate that depression has a stronger effect in CD8+ and CD20+ than in CD4+ cells." (PMID 24996455, 2014). "Lastly, HIV patients with depression are less adherent to antiretroviral therapy (ART), and have lower CD4 counts along with an unfavorable general prognosis." (PMID 19265529, 2009). "A higher adherencewas correlated with lower psychiatric distress among caregivers (p =.005), while depression and anxiety increased non-adherence (p =.07) as measured by lower CD4 counts and pharmacy refills." (PMID 40289039, 2025). "CD3 + CD4 + T-helper cells count distinguished patients with depressive symptoms from those with neither depression nor fatigue." (PMID 40399451, 2025). "In the Depression dataset, BHLHE41 showed significant positive correlation with activated B cells (p < 0.01) but negative correlations with macrophages (p < 0.01), natural killer cells (p < 0.05), and effector memory CD4+ T cells (p < 0.05)." (PMID 40508038, 2025). "In UCRS mice, deletion of CD4-specific AHR or RORγt does not influence behaviors that resemble anxiety or depression." (PMID 39655201, 2024). "Patient employment status, most recent CD4 count, months on ART, and chronic non-communicable diseases were factors associated with depression among HIV-positive patients." (PMID 38238489, 2024). "Furthermore, the study demonstrates a strong correlation between the severity of depression and elevated numbers of CD4+ CD40L+ and CD4+ CD69+ cells, as well as increased expression of CD40L on CD8+ cells and HLADR on CD3+ cells." (PMID 38750122, 2024). "Furthermore, we observed a significant positive correlation between IGF2BP1 and immune cells, specifically natural killer T cells, central memory CD4 T cells, and activated CD8 T cells, which has implications for depression immunotherapy." (PMID 38453794, 2024). "The Ministry of Health and partners working on HIV need to strengthen mental health screening and treat depression among PLWHA with due attention on unemployed patients, low CD4 count, patients newly initiated on ART and with co-morbid chronic non-communicable patients." (PMID 38238489, 2024). "The clinical characteristics of participants in this study included treatment duration, CD4 cell count, viral load and ART regimen, none of which were associated with depression." (PMID 39099258, 2024). "Mean age, duration of ART, and CD4 count do not differ significantly between minimal, mild, moderate, and severe depression groups." (PMID 39175522, 2024). "However, among T cell subsets, a negative correlation was suggested between Th2CM cell frequency and anxiety (p = 0.05), whereas a positive correlation was noted between CD4+ TCM cell frequency and depression (p = 0.02)." (PMID 39650285, 2024).
depression (continued). "Additionally, the authors saw that BD patients in hypomania had a lower percentage of activated helper T cells (CD4+CD25+) and activated cytotoxic T cells (CD8+CD25+) compared to patients in remission or depression." (PMID 37662097, 2023). "We also found that children who had their HIV status disclosed to them and those who did not had no statistically significant different outcomes in CD4 percentage, depression status, or mental and emotional status up to 24 months post-intervention." (PMID 37213654, 2023). "In the chronic pro-neuroinflammatory environment that characterizes at least some subcategories of mental disorders, T cells show maladaptive characteristics in terms of a higher CD4/CD8 ratio, along with a decreased cellular immune response in depressive disorder." (PMID 37859501, 2023). "Nevertheless, no increase in CD4+ T cells was observed in postpartum depression patients compared to healthy postpartum women." (PMID 35844577, 2022). "Regarding CD4, viral load, and the presence of symptoms of depression and anxiety, no statistical differences were observed." (PMID 35719265, 2022). "At the same time, the percentages of IL-10-producing and FoxP3-expressing CD4+ T-cells (with CD3/CD28-stimulation) was higher in MS patients without depression." (PMID 36189272, 2022). "This study evaluated associations between GSH concentrations, CD4 and CD8 lymphocyte counts, self-esteem, socio-familiar support, and symptoms of anxiety and depression in young adults who apparently had no current clinical diagnosis." (PMID 35069302, 2021). "Decreases in IL-2, IL-4 productions, and CD4 percentage were strictly independent of anxiety and depression rates, as there were no more significant differences between the two groups given the HADS scores for anxiety and depression." (PMID 34987425, 2021). "Although biochemical parameters were within reference ranges, glutathione, CD4, and CD8 tended to be lower in participants with anxiety and depression symptoms, which may be of predictive value." (PMID 35069302, 2021). "Polysomnographic recordings for sleep quality assessment, Beck Depression Inventory (BDI), Profile of Mood States(POMS), Rosenberg Self-Esteem Scale (RSES), number of CD3+, CD4+, CD8+ T cells count and CD4/CD8 ratio were measured before and at the end of the study after six months." (PMID 34394237, 2020). "The strength of the correlation was moderate at baseline except for the clinical outcome variables of CD4, HBG and weight and local measures of depression and stress which were small but increased during follow-up which is attributed to the effect of NAMWEZA intervention." (PMID 31996246, 2020). "The combination of HIV and depression has been shown to lower the likelihood of receiving antiretroviral treatment (ART), worsen ART adherence and result in higher viral loads with a decline in CD4 cell count." (PMID 31402989, 2019). "Similarly, in order to predict the CD4 rate based on PTSD and depression severity, a further stepwise hierarchical multiple regression analysis was used." (PMID 30847322, 2019). "It was inconsistent with a study conducted in Cameron, Harar and India, which revealed depression were seen among participant with low CD4 count, unemployed, having poor social support, no or low family income and unmarried." (PMID 30909970, 2019). "One study conducted in South Africa found that patients with severe depression had higher odds of late testing, defined as presenting within 3 months of diagnosis with a CD4 count ≤ 200, as compared to those without depression." (PMID 31317365, 2019). "HIV+ mono‐infected women characteristics were: age (Mean 41.29, SD = 9.03 years), Depression Scale [BDI‐II] scores (Mean 12.86, SD = 11.68), CSF Viral (Mean 0.94, SD = 0.92), CD4 Nadir (Mean 389.83, SD = 240.35), current CD4 (Mean 651.48, SD = 299.15), and CPE of ART (Mean 3.40, SD = 2.75)." (PMID 29671462, 2018).